MMP9 (matrix metallopeptidase 9)
Diseases named in the same sentence as MMP9 in open-access papers (continued):
Sharing a sentence is not in itself a finding about the gene and the disease.
atopic dermatitis (10 papers, 2019 to 2025). "For example, higher levels of MMP-9 have been found in patients with chronic spontaneous urticaria, atopic dermatitis, and allergic rhinitis." (PMID 39088141, 2024). "We also investigated the regulatory effects of dhAvD on CCL20 and IL-23, keratinocyte-derived factors that enhance Th2 cytokines that are highly expressed in atopic dermatitis, and their downstream molecules, MMP-9 and MMP-12." (PMID 39329899, 2024). "Although higher levels of MMP-9 were reported in atopic dermatitis skin wash samples compared to normal controls, our investigation group did not detect a difference in the MMP-9 levels in GCF between Atopic Dermatitis patients and healthy controls." (PMID 36077255, 2022). "IL-13 is co-expressed with MMP-9 in skin samples from atopic eczema patients and it also increases MMP-9 synthesis in cultured keratinocytes." (PMID 31134198, 2019). "The ELISA experiment confirmed that propolis reduced the levels of MMP-9 and IL-2 in UBV-induced allergic dermatitis of HSF cells in a dose-dependent manner." (PMID 40232010, 2025). "There were 28 core targets related to UVB-induced allergic dermatitis, of which hub proteins were TNF-α, NFKB1, MMP-9, and IL-2." (PMID 40232010, 2025). "Serum MMP9 levels have previously been shown to be higher in adult asthmatic patients compared to controls and both MPO and MMP9 are upregulated in children with atopic dermatitis." (PMID 33722194, 2021).
Autoimmunity (10 papers, 2009 to 2025). The occurrence of an immune reaction against the organism's own cells or tissues. "As a contrast, instead of a disease-causing function in organ-specific autoimmunity, a protective role has been described for MMP-9 in systemic autoimmune disease and also this role seems to depend on proteolytic antigen processing." (PMID 30273366, 2018). "Together, these observations provide a mechanistic rationale for IFN-I–targeted therapies in photosensitive autoimmunity and identify MMP9+ monocyte-derived dendritic cells as a tractable, disease-relevant cellular target." (PMID 40894544, 2025). "Cleavage of myelin basic protein or type II gelatins by MMP-9 will produce remnant epitopes and contribute to the development of autoimmunity." (PMID 19272186, 2009). "Moreover, MMP9 can also cleave myelin compounds, such as type II gelatins and myelin basic protein, leading to the generation of epitopes that induce autoimmunity." (PMID 31440381, 2019). "Indeed, the cleavage of myelin basic protein or type II gelatins by MMP-9 will generate remnant epitopes and contribute to develop autoimmunity." (PMID 23555760, 2013). "For that reason, we crossed faslpr mice, prone to systemic autoimmunity, with mmp-9-/- mice to dissect the net effect of MMP-9 on EAE development on short- and long-terms in an antigen-driven model of organ-specific autoimmunity." (PMID 30273366, 2018).
chorioamnionitis (10 papers, 2001 to 2025). A morphologic finding indicating inflammation of the fetal sac membranes. "A large biomarker associated with chorioamnionitis, and premature rupture of membranes is the increase of MMP‐9, a gelatinase enzyme with the capacity to degrade different components of the robust extracellular matrix of fetal membranes." (PMID 39575516, 2024). "Several studies have shown that increased levels of interleukin (IL)-6, matrix metalloproteinase (MMP)-9, and complement split products (C3a and C4a) in AF are associated with both intra-amniotic infection and preterm parturition." (PMID 29743041, 2018). "Similarly, our previous study found that serum CRP has a diagnostic performance similar to that of IL-6 and MMP-9 in AF for the detection of histologic chorioamnionitis." (PMID 29743041, 2018). "Intra-amniotic infection and preterm delivery are associated with high MMP-8 and MMP-9 concentrations in amniotic fluid and in the fetal membranes." (PMID 20868473, 2010). "Therefore, several studies have investigated the high expression of MMP-9 in AF associated with intra-amniotic infection, and found AF MMP-9 levels to be the strongest predictor of intra-amniotic infection in preterm labor." (PMID 29743041, 2018). "Additionally, clinical evidence supports that MMP-9 is an enzyme that increases in the amniotic fluid of women with preterm labor and suspected intra-amniotic infection." (PMID 26446923, 2015). "Notably, we found that nobiletin significantly decreased the expression and release of pro-inflammatory cytokines, and MMP-9 gene expression and secretion of pro MMP-9 in fetal membranes obtained at preterm after spontaneous labour and delivery; both in the absence and presence of chorioamnionitis." (PMID 25238390, 2014). "To date, several studies have identified maternal blood biomarkers that are predictive of histological chorioamnionitis, including various host proteins secreted in response to microbial pathogens, such as serum CRP, MMP-9, IL-6, S100 calcium-binding proteins A8/A9 and IGFBP-1." (PMID 34046191, 2021). "Plasma MMP-9, C3a, and C5a levels did not predict intra-amniotic infection or imminent preterm delivery." (PMID 29743041, 2018). "Plasma MMP-9, C3a, and C5a levels could not predict intra-amniotic infection or imminent preterm delivery." (PMID 29743041, 2018). "However, to our knowledge, no studies have investigated the changes in MMP-9 levels in maternal plasma in relation to intra-amniotic infection and imminent preterm delivery in the setting of preterm labor." (PMID 29743041, 2018).
chronic rhinosinusitis (10 papers, 2010 to 2023). Chronic form of sinusitis. "MMP-9 degrades the extracellular matrix and is involved in tissue remodeling; MMP-9 gene polymorphisms have been demonstrated to affect susceptibility to the development of chronic rhinosinusitis with NP in Chinese patients." (PMID 25573100, 2015). "S. aureus has been shown to induce the tissue remodeling factors MMP2, MMP9, and TIMP1 in mucosal explants from chronic rhinosinusitis (CRS) patients." (PMID 28083514, 2016). "In addition, vitamin D inhibited the expression and activity of MMP-9 in human lung fibroblasts and MMP-2 in patients with chronic rhinosinusitis." (PMID 36845046, 2023).
delirium (10 papers, 2014 to 2025). A disorder characterized by confusion; inattentiveness; disorientation; illusions; hallucinations; agitation; and in some instances autonomic nervous system overactivity. "ROS scavenger prevented the reduction in TJ proteins and restored the permeability of BBB as well as reduced the levels of CypA/MMP9, and further alleviated delirium-like behavior induced by anesthesia/surgery." (PMID 36337710, 2022). "In general, these findings demonstrated that the CypA/MMP9 signaling pathway was the potential mechanism for delirium-like behavior." (PMID 36337710, 2022). "Our results showed that ROS mediated the harmful effects on BBB integrity and delirium-like behavior after anesthesia/surgery, potentially via the CypA/MMP9 signaling pathway." (PMID 36337710, 2022). "We, therefore, hypothesized that ROS may contribute to anesthesia/surgery-induced BBB damage and delirium-like behavior via the CypA/MMP9 pathway." (PMID 36337710, 2022). "Another study revealed that, after adjusting for covariates, lower plasma concentrations of matrix metalloproteinase-9 (MMP-9) and protein C and higher concentrations of soluble tumor necrosis factor receptor-1 (sTNFR1) were associated with increased risk of delirium." (PMID 27011789, 2016). "Therefore, we assumed that the CypA/MMP9 pathway may be engaged in the development of delirium-like behavior induced by anesthesia/surgery, and that ROS-induced BBB disruption may be a possible pathway that should be explored." (PMID 36337710, 2022). "Finally, AZGP1, MMP-9, neopterin, phenylalanine–tyrosine ratio, SERPINA3, thioredoxin, and 8-iso-prostaglandin F2α were linked to postoperative delirium." (PMID 31263968, 2019). "Irrespective of a COVID-19 infection, serum concentration of MMP-9 and GFAP were significantly higher in delirium." (PMID 39352661, 2025). "Anesthesia/surgery induce the release of ROS, and then activate the expression of CypA/MMP9 cascade, resulting in BBB dysfunction and delirium-like behavior." (PMID 36337710, 2022). "Molecules identified for this criterion from the RNAseq dataset with a known or possible involvement in encephalopathy and delirium included miR-320a-3p, ACHE, TSPO, and TIMP1, which interacted with MMP9." (PMID 34573990, 2021). "Due to the inhibition of CypA/MMP9 could attenuate anesthesia/surgery-induced BBB damage and synaptic plasticity proteins decrease, we next examined whether CsA could reverse delirium-like behavior induced by anesthesia/surgery." (PMID 36337710, 2022).
disc degeneration (10 papers, 2016 to 2025). "Neutrophils are the sole cellular source of MMP-9, which induces disc degeneration by promoting the loss of type II collagen." (PMID 40303407, 2025). "The researchers showed that MMPs played a dominant role in IDD and that elevated levels of MMP-2 and MMP-9 were associated with grading of degenerative disc disease." (PMID 35754493, 2022). "Meta-analysis found that MMP-9 rs17576 increased significantly the risk of disc degeneration [48•]." (PMID 30464887, 2018). "MMP-9 degrades extracellular matrix components in the disc, such as collagen and proteoglycans, and its expression level is positively correlated with the severity of disc degeneration and herniation." (PMID 41346614, 2025). "The protein expression of metalloprotease MMP9 is decreased at 15 days of disc degeneration." (PMID 26997908, 2016). "In addition, the -1562C/T polymorphism of the MMP-9 gene is associated with IDD susceptibility in young adults, and downregulation of miR-133a promotes collagen II loss by targeting MMP-9, further contributing to disc degeneration." (PMID 41346614, 2025). "Three, recent studies suggest that expression of MMP-3, MMP-9, and MMP-13 is increased in degenerative disc disease." (PMID 30704538, 2019). "In addition, factors such as IL-1β, MAPK14, MMP9, and MMP3 can contribute to inflammation and matrix degradation, potentially further interacting with Wnt signaling to exacerbate disc degeneration." (PMID 39623712, 2025). "A single impact applied to the lumbar disc without causing structural damage to the lumbar spine also triggered significant upregulation of Piezo1, NLRP3 inflammatory vesicles, catabolic (MMP-9, MMP-13) and pro-inflammatory gene (IL-1β) expression and induced disc degeneration (IDD)." (PMID 35154133, 2022).
Ewing sarcoma (10 papers, 2012 to 2025). A small round cell tumor that lacks morphologic, immunohistochemical, and electron microscopic evidence of neuroectodermal differentiation. "It is also well established that MMP2 and MMP9 are expressed in Ewing sarcoma and closely associated with Ewing sarcoma invasion and metastasis." (PMID 31370265, 2019). "Finally, we found that WT1 expression is correlated with VEGF expression, MMP9 expression, and microvessel density in samples of primary Ewing sarcoma." (PMID 24810959, 2014). "To investigate whether VEGF and MMP9 expression in primary Ewing sarcoma correlate with WT1 expression, we performed immunohistochemical analysis of 21 paraffin-embedded Ewing sarcoma samples." (PMID 24810959, 2014). "Because our WT1-expressing xenografts showed more MMP9 expression by immunohistochemistry, we were interested in whether MMP9 is also a direct WT1 target gene in Ewing sarcoma cells." (PMID 24810959, 2014). "Finally, WT1 expression was correlated with VEGF expression, MMP9 expression, and microvessel density (as reflected by CD31 expression) in samples of primary Ewing sarcoma." (PMID 24810959, 2014). "Also, the levels of expression of the well-known pro-angiogenic molecules (VEGF and b-FGF) and pro-invasive molecules (MMP-2 and MMP-9) were highly inhibited following combination of EWS shRNA plasmid transfection and TFL treatment in Ewing’s sarcoma xenografts." (PMID 27547487, 2014). "The concept of WT1 as a global regulator of angiogenesis is further supported by our demonstration MMP9 is a direct target of the transcriptional regulatory activity of WT1 and identification of a small panel of additional pro-angiogenic molecules upregulated by WT1 in Ewing sarcoma cell lines." (PMID 24810959, 2014).
kidney cancer (10 papers, 2013 to 2025). Primary or metastatic malignant neoplasm involving the kidney. "In kidney cancer cells, Pten knockout caused changes in epithelial to mesenchymal transition marker expression, with downregulation of E-cadherin and upregulation of Snail, Mmp9, and Acta2 (α-SMA)." (PMID 37673853, 2023). "In conclusion, MMP-9 can be used as a pan-cancer prognostic biomarker involving immune infiltration, especially in kidney cancer." (PMID 35178444, 2022). "Here, we found that MMP-9 promotes cancer development and progression in some cancers, suggesting that MMP-9 expression can be used to predict metastasis, especially in kidney cancer." (PMID 35178444, 2022). "A study found that psoralen could slow the progression of kidney cancer by inhibiting the expression of MKI67, PCNA, MMP2 and MMP9 as well as the proliferation, invasion, and migration of kidney cancer cells HTB-47 and CRL-1932." (PMID 36627680, 2023). "For instance, earlier studies demonstrated the overexpression of MMP9, MMP12, MMP14, and MMP16 in breast and kidney cancers, emphasizing their role in tumor progression and metastasis." (PMID 39493455, 2024). "In kidney cancer, E2F1 could enhance the metastatic potential of tumor cells through the activation of matrix metalloproteinase (MMP) 2 and MMP9." (PMID 37077419, 2023). "Furthermore, we showed that MTA1 is up-regulated in ccRCCs, which contributes to the migration and invasion of human kidney cancer cells by mediating the expression of MMP2 and MMP9 through the NF-κB signaling pathway." (PMID 33059651, 2020). "In spite of recent evidence and interest among biologists and oncologists, the serum and urine levels of MMP-9, NGAL and their complex (MMP-9/NGAL) appear to not provide an adequate test to identify kidney cancer." (PMID 23760084, 2013).
Marfan syndrome (10 papers, 2013 to 2025). A disorder of the connective tissue. "Enhanced activity of MMP-13 along with increased levels of active MMP-9 acts as an important biomarker for the early diagnosis of Marfan syndrome." (PMID 37342498, 2023). "Patients with ATAA, AAA and Marfan syndrome have shown elevated MMP-9 production and activity in their aortas." (PMID 37238945, 2023). "The association of an enhanced activity by MMP-13 with an increased amount of active MMP-9 is an important biomarker for the early diagnosis of Marfan syndrome, before genetic assessment." (PMID 31340803, 2019). "Abnormal VSMCs induced the expression of matrix metalloproteinase 9 (MMP-9) mediating elastolysis in a mouse model of Marfan syndrome." (PMID 23516544, 2013). "The association of an enhanced activity by MMP-13 with an increased amount of active MMP-9 might be an important biomarker for the diagnosis of Marfan syndrome." (PMID 31340803, 2019). "MMPs (matrix metalloproteinases) are proteinases involved in fragmentation of elastic fibers in Marfan syndrome, with MMP-2 and MMP-9 specifically involved in the pathogenesis of Marfan aneurysm formation." (PMID 36140728, 2022).
metastasis (10 papers, 1998 to 2022). The spread or migration of cancer cells from one part of the body (where they first appeared) to another. "Furthermore, high expression of MMP9 was significantly associated with invasion depth, lymph node metastasis and later clinical stage of Kazakh ESCCs." (PMID 28423526, 2017). "In addition, the MMP-9 score was greater if patients previously had central lymph node metastasis, lateral lymph node metastasis, or an advanced tumor-node metastasis stage (III + IV)." (PMID 36551933, 2022). "Moreover, we have validated some previously reported overexpressed genes such as TGFB1, IBSP, MMP9, or ITGB3 in bone metastasis; CRYAB, NRCAM, and SOX2 in brain metastasis; VEGF and IL6 in lung metastasis; and CYP4F3 in liver metastasis." (PMID 34051058, 2022). "ELISA analysis reveals that the latent form of MMP-9 is present in both liver metastasis and paired adjacent normal liver tissue." (PMID 9703281, 1998). "Therefore, the serum levels of VEGF and MMP-9 can be used as markers for the diagnosis of breast IDC and may also be valuable for the prediction of lymph nodes metastasis." (PMID 24944618, 2014).
Pleural effusion (10 papers, 2011 to 2023). The presence of an excessive amount of fluid in the pleural cavity. "The diagnostic efficacy of SMRP combined with CA125, MMP-7, and MMP-9 in pleural effusion for malignant pleural effusion and BPE are better than single index, which has certain clinical values for the selection of early intervention scheme for BPE patients." (PMID 36705352, 2023). "The levels of SMRP, CA125, MMP-7, and MMP-9 in the pleural effusion were determined by enzyme linked immunosorbent assay." (PMID 36705352, 2023). "We found that in the malignant group, the levels of SMRP, CA125, MMP-7, and MMP-9 in pleural effusion were higher than those in the benign group, and all of which had a statistical significance (P = .01)." (PMID 36705352, 2023). "The clinical data in the present study demonstrate the elevated effusion levels of TNF-α, MMP-1 and MMP-9 in TBP and the association of these mediators with amount of pleural effusion and area of pleural fibrosis." (PMID 26367274, 2015). "Expression of SMRP, CA-125, MMP-7, and MMP-9 in pleural effusion." (PMID 36705352, 2023). "Compared to pleural effusions, MMP-9 levels in ascites were decreased." (PMID 31608201, 2019).
primary open-angle glaucoma (10 papers, 2010 to 2025). "Single nucleotide polymorphisms (SNPs) in the MMP9 gene are associated with a higher risk of primary open-angle glaucoma (POAG) and NTG." (PMID 38983026, 2023). "The genotype distribution of -1562C>T MMP9 gene polymorphisms in patients with open-angle glaucoma (POAG) and angle closure glaucoma (PACG) according to CDR and IOP." (PMID 29432439, 2018). "Activity of uPA and MMP9 has also been linked to gliosis and retinal ganglion cell death in experimental models of open angle glaucoma)." (PMID 23951261, 2013). "Functional gene polymorphisms of these MMPs such as MMP1 −1607 1G/2G (rs1799750), MMP2 −1306 C/T (rs243865), MMP2 −1575 G/A (rs243866), and MMP9 Q279R (rs17576) are thus plausible candidates as risk factors for open angle glaucomas." (PMID 20808730, 2010). "Ussa and co-workers investigated whether the SNPs of the genes encoding MMP1, MMP2, MMP3, MMP9, and MMP17 were related to the response to latanoprost in 124 Spanish patients with open-angle glaucoma." (PMID 39769228, 2024).